BRCA2 (BRCA2 DNA repair associated)
Diseases named in the same sentence as BRCA2 in open-access papers (continued):
Sharing a sentence is not in itself a finding about the gene and the disease.
breast cancer (continued). "In HR pathway, other miRNAs play an important role in DSB repair: miR-138 targeting H2A.X in osteosarcoma cells, miR-146a and miR-146b-5p targeting BRCA1 in breast cancer, miR-1 targeting BRCA1 in prostate tumor cell lines, and miR-1245 targeting BRCA2 in breast cancer cell lines." (PMID 34094980, 2021). "BRCA2 c.7934delG carrier status was associated with a significantly younger age (p=0.03) at diagnosis of breast cancer compared to non-carriers." (PMID 34660253, 2021). "Three genetic factors are involved in breast cancer progression: high penetrance genetic mutations such as those in the BRCA1 and BRCA2 genes, intermediate penetrance variants such as those in ATM, BARD1, PALB2, and CHECK2 genes, and low-penetrance variants such as SNPs." (PMID 34493284, 2021). "Also in adult patients, tumor mutations, such as in EGFR, BRCA1/BRCA2, and SMAD4 genes, decrease engraftment rates in adenocarcinoma, breast cancer, and pancreatic cancer, respectively." (PMID 33837665, 2021). "This aligns with previous literature of BRCA2 variant carriers receiving RT for breast cancer in which no increase in late toxicity was observed, though the comparison is imperfect given anatomical differences and RT dose rarely exceed 50 Gy in breast RT." (PMID 34001187, 2021). "Interestingly, MIR3613 locus (13q14.2) located near tumor suppressor genes RB1 (13q14.2) and BRCA2 (13q13.1) on chromosome 13 and copy number of this gene segment in breast cancer was frequently altered." (PMID 33494814, 2021). "Three more PALB2 germline PVs producing truncated protein were identified among 81 European FPC family, each of these three family had also history of breast cancer (none of the patients was carrier of BRCA2 mutation)." (PMID 33718150, 2021). "The identification of the first breast cancer susceptibility genes dates back to the nineties when linkage studies led to the identification of the BRCA1 and BRCA2 genes (BReast-CAncer susceptibility gene 1 and 2) carrying likely pathogenic variants that co-segregate with breast cancer in families." (PMID 34439109, 2021). "Indeed, 13–18% of hereditary ovarian cancer cases, and around 5% of hereditary breast cancer cases are due to BRCA1 and BRCA2 mutations." (PMID 34242281, 2021). "However, here we show a patient with biallelic BRCA2 (c.1813dup and c.7796 A > G) diagnosed at age 33 with FA after a hypertoxic reaction to chemotherapy during breast cancer treatment." (PMID 34504103, 2021). "In routine mammography exams, only 0.5% of the cases will have cancer present, however if the patient has the BRCA1 or BRCA2 genetic mutation (colloquially referred to as the “breast cancer gene”), there is a 82% chance of developing cancer during their lifetime." (PMID 33740159, 2021). "BRCA genes are essential DNA double-strand break (DSB) repair, while the mutations in the genes can lead to a predisposition to cancers, including breast cancer and ovarian cancer, with the risk of breast cancer and contralateral breast cancer both increased by BRCA1 and BRCA2 mutations." (PMID 34376160, 2021).
breast cancer (continued). "The ENIGMA (Evidence-based Network for the Interpretation of Germline Mutant Alleles) consortium has been playing an important role to evaluate the clinical significance of sequence variants in high-risk breast cancer genes including BRCA1 and BRCA2 genes since its establishment in 200913." (PMID 34045478, 2021). "Breast cancer 2, early onset (BRCA2) is a tumor suppressor gene." (PMID 33407082, 2021). "Another study with 89% of the population with breast cancer used next-generation sequencing analysis with a 94-gene panel and showed a total of 81 pathogenic/likely pathogenic mutations in 29% of patients including mutations in BRCA1, BRCA2." (PMID 34046273, 2021). "Also, data on the association of HRT use and breast cancer in BRCA1/2 mutation carriers are limited, especially for BRCA2 mutation carriers." (PMID 33885953, 2021). "However, germline structural variants are less frequent in breast cancer genes such as BRCA1 (0.8 to 6.9%) and BRCA2 (5%) in Asian populations." (PMID 34857041, 2021). "On the other hand, the risk estimated from BCRAT is not dependent on the likelihood of being a BRCA1 or BRCA2 mutation carrier, and the relative risks attributed to family history of breast cancer remain constant with age of the consultee." (PMID 34680343, 2021). "In contrast, a first diagnosis of TNBC rather than any other breast cancer subtype was associated with BRCA2 or PALB2 for AA patients, but not for EA patients." (PMID 33479248, 2021). "Breast MRI with contrast has been reported to show a round or oval mass on the chest wall side in BRCA1-associated breast cancer and non-mass enhancement in BRCA2-associated breast cancer." (PMID 34674065, 2021). "Although initial genetic testing results in the KOHBRA study revealed a VUS in 676 patients (278 patients for BRCA1 and 453 patients for BRCA2) out a total of 2,403 breast cancer patients (28.13%, 676/2,403), re-evaluation revealed a lower frequency of VUSs (8.03%, 193/2,403)." (PMID 33875706, 2021). "In Haiti, 6.7% (5 of 75) of patients with breast cancer had a variant in BRCA1, BRCA2, or PALB2." (PMID 33646313, 2021). "In addition, two patients harbored a PV in a PDAC-predisposition and another gene: ATM/FANCE (PDAC patient with colon cancer) and BRCA2/CHEK2 (early-onset breast cancer PDAC patient)." (PMID 34503238, 2021). "For women with breast cancer and a germline BRCA2 mutation, positive ER status does not predict superior survival." (PMID 33597716, 2021). "For BRCA1 heterozygotes, the largest association was seen with the ER-negative PRS313, while for BRCA2 heterozygotes, both the PRS313 and ER-positive PRS313 showed similar associations with contralateral breast cancer risk that were somewhat larger than the ER-negative PRS313 association." (PMID 34113011, 2021). "A prospective cohort study showed that RRSO reduced all-cause mortality in both pre- and postmenopausal women; however, RRSO significantly reduced the risk of breast cancer for BRCA2 pathogenic variant carriers, but not for BRCA1 pathogenic variant carriers." (PMID 34071148, 2021). "Family history could influence breast cancer subtypes potentially owing to the enrichment of inherited genetic mutations such as BRCA1 and BRCA2, which account for 30%–50% of the known mutations that cause breast cancer." (PMID 33737705, 2021). "Preclinical studies suggest that BRCA2-mutated but not BRCA1-mutated breast cancers are responsive to treatment with checkpoint inhibitor monotherapy." (PMID 34067105, 2021). "The most frequently mutated gene (6%) was the BRCA2 gene, even in the absence of breast cancer, as already reported by others." (PMID 34357098, 2021).
breast cancer (continued). "In this study we investigated the associations between an established PRS based on 313 variants for primary first breast cancer and contralateral breast cancer risks among BRCA1 and BRCA2 heterozygotes of European ancestry enrolled in the large international retrospective CIMBA cohort." (PMID 34113011, 2021). "In contrast, TNBC versus other tumor subtype was not more frequent among EA breast cancer cases with pathogenic variants in BRCA2 or PALB2 than among EA cases with no such variants (OR = 0.62 [0.18, 2.09])." (PMID 33479248, 2021). "For carriers of pathogenic variants in BRCA1, the average cumulative risks by age 80 years is 72% (95% confidence interval 65–79%) for breast cancer and 44% (36–53%) for ovarian cancer, and the corresponding estimates for BRCA2 are 69% (61–77%) and 17% (11–25%) respectively." (PMID 33836815, 2021). "Overall mortality was significantly reduced in both subgroup analyses for patients with a history of BRCA1- and BRCA2-mutated breast cancer and no history of breast cancer." (PMID 32862296, 2021). "Importantly, DDX5 interaction with the BRCA2 mutant T207A, found in breast cancer cells from patients, is reduced compared to wild-type BRCA2, and R-loops levels are increased in cells that overexpress this variant." (PMID 34359660, 2021). "Their analysis revealed a prevalence rate of 2.2% among early onset breast cancer BRCA1/BRCA2 mutation negative patients, unselected for family history and 0.9% if there were no additional features indicative of LFS." (PMID 33245408, 2021). "In Morocco, BRCA1 and BRCA2 mutations have been extensively investigated for breast cancer but not so for prostate cancer." (PMID 34242281, 2021). "Undifferentiated (G3) basal-like ductal breast cancers (triple-negative) are the most recurrent in BRCA1 carriers, while fewer data are available about BRCA2 carriers, although BRCA2 tumors seem to be more similar to sporadic breast cancer both for histological and molecular characteristics." (PMID 34572941, 2021). "In prior work, a mutational frequency of 0.4% was observed for ATM alterations in 7,675 BRCA1 and BRCA2-negative breast cancer patients in a Chinese population and a mutational frequency range of 0.45 to 1.0% was found in the US and Europe." (PMID 34471951, 2021). "BRCA2 (breast cancer susceptibility gene 2) was identified in 1995 by Wooster and colleagues, by analyzing BRCA1 mutation-negative breast cancer families, including male patients with breast cancer." (PMID 32862296, 2021). "We next determined the power of the competing RVAS tests to identify the 8 breast cancer risk genes (BRCA1-Missense, BRCA1-LoF, BRCA2-Missense, BRCA2-LoF, PALB2, BRIP1, CHEK2 and BARD1) at the three TIER levels 5%, 0.1% and 0.01% and at three levels of VE of 2%, 1% and 0.5% (Iberian: S6 Fig)." (PMID 33606672, 2021). "It is speculated that the increased incidence of breast cancer in women who carry BRCA1, BRCA2 or PALB2 germline mutations is due to deficiencies in DNA damage repair." (PMID 35187501, 2021). "Longer use of OC, especially before the first full-term pregnancy, was also associated with an increased risk of breast cancer for both BRCA1 and BRCA2 mutation carriers (HR = 1.49; 95% CI = 1.05–2.11 for BRCA1 subjects and HR = 2.58; 95% CI = 1.21–5.49 for BRCA2 subjects)." (PMID 33925599, 2021). "Cytoplasmic retention renders this RAD52 variant nonfunctional leading apparently to attrition of BRCA2-deficient breast cancer cells." (PMID 34887904, 2021).
breast cancer (continued). "The response rates were 2% for complete responses (CR: olaparib for BRCA2 mutation and high HRD score in prostate cancer, and capivasertib for PIK3CA mutation in breast cancer), 17% for partial responses (PR), 16% for stable disease (SD), and 65% for progressive disease (PD)." (PMID 34006291, 2021). "Notably, the breast cancer genes BRCA1 and BRCA2, two important HR players, are the most frequently mutated genes in familial breast and ovarian cancer." (PMID 33923105, 2021). "Interestingly, the treatment was shown to prevent contralateral breast cancer by 50% and demonstrated a 44% risk reduction of developing a second breast cancer in both BRCA1 and BRCA2 WT and mutant conditions." (PMID 35008272, 2021). "In addition to ovarian and breast cancers, loss-of-function mutations in BRCA1 and BRCA2 genes are also linked to an increased risk of pancreatic cancer, with ~ 4 to 7% of pancreatic cancer patients harboring germline BRCA mutations." (PMID 33407459, 2021). "Therefore, from breast cancer studies, it was first derived that men with BRCA1 and BRCA2 mutations were at higher risk for PCa." (PMID 34830851, 2021). "Germline mutations in BRCA2 are highly penetrant for breast cancer and ovarian cancer, but the mechanism of BRCA2 mutation in CRC is still not clear." (PMID 35860598, 2021). "Genetic analysis results showed that 36 out of 354 tested breast and ovarian cancer patients were BRCA1/2 mutation carriers (31 breast cancer cases and 5 ovarian cancer patients), including 21 patients with BRCA1 mutation and 15 patients carrying BRCA2 mutation." (PMID 34490083, 2021). "Indeed, in breast cancer patients with variants such as in BRCA1, BRCA2, and ATM, it is recommended that the contralateral breast dose in mammography and radiotherapy be minimized in order to prevent secondary carcinogenesis." (PMID 34608183, 2021). "In conclusion, the present data indicate that BRCA1/BRCA2 sequencing may be considered for postmenopausal breast cancer patients having a family history of cancer." (PMID 34287479, 2021). "Inherited mutations in BRCA1, BRCA2, and PALB2 cause a high risk of breast cancer." (PMID 33893322, 2021). "Clinicopathologic characteristics associated with undergoing CPM included a family history of breast cancer, age at diagnosis of breast cancer, white race, tested for BRCA1 or BRCA2 mutation, clinical tumor stage, and lobular histology as well as patients who underwent reconstructive surgery." (PMID 33922702, 2021). "The impact of various breast-cancer treatments on patients with a BRCA2 mutation has not been studied." (PMID 33597716, 2021). "BRCA2 mutations have been widely reported in breast cancer, but have not been extensively studied in GC." (PMID 33933102, 2021). "Breast cancer groups bearing germline and somatic BRCA2 mutations as well as non-mutated patients were characterized by the upregulation of luminal subtype signatures such as ESR1, TFF1, TFF2." (PMID 33525353, 2021). "Such knowledge could have an impact on the prediction of early cancer development, and therefore, be used to advise the timing of preventive therapies, and targeted therapies of BRCA2 related breast cancer in the future as discussed here above." (PMID 35052422, 2021). "However, BRCA1 carriers were more likely to have triple negative breast cancer (p=0.002) and BRCA2 carriers were more likely to have luminal B breast cancer tumors (p=0.000078)." (PMID 34490083, 2021). "BRCA1-associated breast cancers have aggressive pathological traits and are mainly hormone receptor-negative, whereas BRCA2-associated breast cancers have sporadic characteristics and are predominantly hormone receptor-positive." (PMID 34828379, 2021). "The same kind of genetic background may also apply to breast cancers, for which BRCA1 and BRCA2 are prominent predisposing genes for the early onset component but at higher ages other genes are likely to contribute." (PMID 34503195, 2021).
breast cancer (continued). "Not all women with mutations in BRCA1 or BRCA2 develop breast cancer and little is known about the factors that influence penetrance, making it difficult to personalize decisions concerning risk-reducing interventions." (PMID 33649363, 2021). "This topic remains controversial for the reported differences in BRCA1 and BRCA2 pathogenic variant carriers and for the different effects of pregnancy on breast cancer risk according to age also in the general non-BRCA carrier population." (PMID 34503502, 2021). "Due to the high incidence of breast cancer worldwide and its relatively high mortality and morbidity, it is important to implement appropriate screening tests which enable rapid and efficient mutation screening in the BRCA1 and BRCA2 genes." (PMID 33918338, 2021). "The histology of the BRCA2-mutated breast cancer tissue is almost similar to those without BRCA mutations, and the histological nuclear grade is generally high." (PMID 32862296, 2021). "RAD52 is shown to be associated with breast cancer susceptibility genes BRCA1 and BRCA2." (PMID 34484285, 2021). "There are also three identified breast cancer cluster regions in BRCA2: c.1 to c.596 (BCCR1; RHR = 1.71; 95% CI, 1.06–2.78; P = .03), c.772 to c.1806 (BCCR13; RHR = 1.63; 95% CI, 1.10–2.40; P = .01), and c.7394 to c.8904 (BCCR2; RHR = 2.31; 95% CI, 1.69–3.16; P = .00002)." (PMID 34711195, 2021). "We described the geographic distribution and relative prevalence of 27 different FANCM PTVs detected in 114 female European breast cancer probands with no pathogenic variants in BRCA1 or BRCA2 genes." (PMID 31991861, 2020). "Combining the Japanese cases with 34 cases from TCGA breast cancer cases, we tested this hypothesis using a total of 64 cases with germline BRCA1/BRCA2 variants." (PMID 33067557, 2020). "It is important to note that genetic susceptibility to EOC cancer does not exist in isolation, and variants conferring increased ovarian cancer risk also often increase the risk of developing other cancers—most notably breast cancer in BRCA1 and BRCA2, and colon cancer in Lynch syndrome." (PMID 33086730, 2020). "Moreover, BRCA2 c.4307T>C occurred in a hepatocellular carcinoma patient with a family history of breast cancer." (PMID 32879886, 2020). "Despite BRCA2 SNPs not showing an association with breast cancer using the traditional approach, this gene appears associated in the haplotype analysis." (PMID 33126731, 2020). "Pathologically, familial breast cancers due to BRCA1 mutations differ to those caused by BRCA2 mutations and non-familial breast cancer." (PMID 32025336, 2020). "All of the patients in the current study had germline BRCA2 mutations, and it will be important to see if these relationships exist in breast cancer patients with somatic but no germline mutations." (PMID 32939053, 2020). "In breast cancer, carriers of pathogenic BRCA1 or BRCA2 variants are faced with the decision about whether to undergo prophylactic mastectomy as opposed to serial imaging." (PMID 32820175, 2020). "The most important reason for this is that MRI is not affected by breast density and BRCA1 and BRCA2 mutation carriers are associated with a diagnosis of breast cancer at a young age, resulting in dense breasts." (PMID 31734900, 2020). "Patients with BRCA1-associated breast cancers are younger than those with the BRCA2 mutation and those without mutation." (PMID 32322271, 2020). "Provision of genetic counselling and genetic testing for rare variants in breast cancer predisposition genes such as BRCA1 and BRCA2 can lead to better management of risk, but these only explain a small fraction of breast cancer cases in the general population." (PMID 32737321, 2020). "Both of these approaches identified driver gene mutations in breast cancer-associated genes, such as MUC16, NF1, and BRCA2, suggesting that using different predictive computational tools improves the sensitivity and specificity in identifying cancer somatic mutations." (PMID 32650480, 2020).